MT-TS2 (mitochondrially encoded tRNA-Ser (AGU/C) 2)
Synonyms: TRNS2; RP8; formerly MTTS2
Gene: Mitochondrial transfer RNA gene on chromosome MT (12,207 to 12,265, forward strand). Ensembl gene ENSG00000210184.
Gene-disease validity (ClinGen):
ClinGen rates the evidence that MT-TS2 causes each of these diseases.
mitochondrial disease (mitochondrial): Definitive.
Diseases named in the same sentence as MT-TS2 in open-access papers:
MT-TS2 is named in the same sentence as 1 disease in open-access papers, as found by Europe PMC text mining. Sharing a sentence is not in itself a finding about the gene and the disease. The quoted sentences say what the papers report.
viral infection (1 paper, 2015). "Among them, 22 genes (Gm26130, mt-Ts2, Mgst2, Cyp7a1, Vps45, etc.)were clustered as a hot block next to a block containing Irf7 gene that is the master regulator for the induction of type I interferon during viral infection." (PMID 25902143, 2015).